ENOSF1 (enolase superfamily member 1)
Description:
Plays a role in the catabolism of L-fucose, a sugar that is part of the carbohydrates that are attached to cellular glycoproteins. Catalyzes the dehydration of L-fuconate to 2-keto-3-deoxy-L-fuconate by the abstraction of the 2-proton to generate an enediolate intermediate that is stabilized by the magnesium ion.
Synonyms: rTS; TYMSAS; HSRTSBETA; FUCD
Tractability: PROTAC: UniProt records ubiquitination sites on it; ubiquitination databases record sites on it.
Safety:
Unwanted effects reported when the protein is acted on. In parentheses: how it was acted on, where the effect was seen, and who reports it.
asthenia (source: ClinPGx)
drug toxicity (source: ClinPGx)
hand-foot syndrome (source: ClinPGx)
nausea and vomiting (source: ClinPGx)
side effects (source: ClinPGx)
Gene: Protein-coding gene on chromosome 18 (670,318 to 712,722, reverse strand). Ensembl gene ENSG00000132199.
Subcellular location: Mitochondrion
Gene Ontology:
Molecular function: L-fuconate dehydratase activity; magnesium ion binding; hydro-lyase activity
Biological process: carbohydrate catabolic process; amino acid catabolic process
Cellular component: mitochondrion
Genetic constraint (gnomAD): Loss-of-function variants: 64 observed, 63.74 expected, observed/expected ratio (o/e) 1, 90% interval 0.82 to 1.24. The upper end of that interval is the gene's LOEUF score, 1.24, which puts it in group 5 of 6, group 1 being the genes least tolerant of losing a copy. Missense variants: 571 observed, 562.96 expected, observed/expected ratio (o/e) 1.01, 90% interval 0.95 to 1.09. Synonymous variants: 217 observed, 214.66 expected, observed/expected ratio (o/e) 1.01, 90% interval 0.9 to 1.13.
Homologues: Orthologues: chimpanzee ENOSF1 (99% identical), macaque ENOSF1 (98% identical), rabbit ENOSF1 (91% identical), pig ENOSF1 (88% identical), guinea pig ENOSF1 (88% identical), dog ENOSF1 (81% identical), tropical clawed frog enosf1 (78% identical), zebrafish enosf1 (73% identical).
Diseases named in the same sentence as ENOSF1 in open-access papers:
ENOSF1 is named in the same sentence as 17 diseases in open-access papers, as found by Europe PMC text mining. Sharing a sentence is not in itself a finding about the gene and the disease. The quoted sentences say what the papers report.
colorectal cancer (2 papers, 2015). A primary or metastatic malignant neoplasm that affects the colon or rectum. "We evaluated the association between nine polymorphisms in MTHFR, CDA, TYMS, ABCB1, and ENOSF1 and adverse reactions, dose reductions, treatment delays, and overall toxicity in 239 colorectal cancer patients treated with capecitabine-based regimens." (PMID 25691056, 2015).
gastric cancer (2 papers, 2018 to 2023). A primary or metastatic malignant neoplasm involving the stomach. "ENOSF1, a mitochondria enzyme that have been shown as a serum biomarker for gastric cancer, was the top hub with 150 differential pairs." (PMID 30577836, 2018). "The expression level of ENOSF1 in the serum of gastric cancer patients was significantly higher than that of healthy controls, which could be used as a potential gastric cancer serum biomarker." (PMID 36642706, 2023).
Hand-foot syndrome (2 papers, 2020 to 2022). "This “C-A-ins” haplotype (rs699517-rs2790-rs151264360) is associated with both reduced TYMS and increased ENOSF1 expression as well as with severe hand-foot syndrome." (PMID 35931051, 2022). "A recently published meta-analysis reported that the polymorphism c.742-227G>A (rs2612091) within the Enolase Superfamily Member 1 gene (ENOSF1) was associated with the development of severe hand-foot syndrome (HFS) in 5FU/Cp-treated patients." (PMID 33086767, 2020). "The altered ENOSF1/TYMS ratio could also be the underlying basis of the severe hand-foot syndrome that is observed in a subset of cancer-affected individuals treated with 5-fluorouracil and related cancer drugs." (PMID 35931051, 2022).
colon cancers (1 paper, 2011). "Results of previous studies suggest involvement of the β splice form of ENOSF1 in breast and colon cancers." (PMID 21943404, 2011).
Hypertension (1 paper, 2026). The presence of chronic increased pressure in the systemic arterial system. "Among those, CMTM5, ITGA2B, and SLC24A3 are implicated in platelet function and cardiovascular complications, whereas ENOSF1 has been previously linked to hypertension." (PMID 41500120, 2026).
cancer (6 papers, 2011 to 2023). A tumor composed of atypical neoplastic, often pleomorphic cells that invade other tissues. "Expanding on these results, we used bioinformatics to find more animal homologues of the ENOSF1 splice form associated with increased cancer risk in human patients: hsENOSF1β." (PMID 21943404, 2011). "One of our major findings, increased apoptosis following in vivo ENOSF1 knockdown, has implications for cancer therapy." (PMID 21943404, 2011). "Human cancer cell lines have three known ENOSF1 splice forms (α, β, and γ)." (PMID 21943404, 2011).
tumor (4 papers, 2011 to 2023). "In this study, the expression of ENOSF1 was significantly reduced in OC tissue, and low expression predicted a good prognosis, indicating that ENOSF1 acted as a tumor suppressor gene in OC." (PMID 36642706, 2023). "Given that TYMS is a chemotherapy target, an rs495139-associated increase in ENOSF1 and decrease in TYMS expression might suggest a favorable tumor profile for patient survival." (PMID 30134598, 2018). "We hypothesized that genetic polymorphisms could perturb the TYMS mRNA-antisense mRNA autoregulatory complex by either increasing TYMS or decreasing ENOSF1 gene expression to promote uncontrolled DNA synthesis and tumor growth." (PMID 30134598, 2018).
ENOSF1 also shares sentences with these, for which no sentence is quoted: breast carcinoma (1 paper); chronic lymphocytic leukemia (1); DPYD deficiency (1); dyskeratosis congenita (1); ectodermal dysplasia (1); gastrointestinal neoplasms (1); mucinous ovarian carcinoma (1); ovarian carcinoma (1); trigonocephaly (1); uveal melanoma (1).